IL6 (interleukin 6)
Diseases named in the same sentence as IL6 in open-access papers (continued):
Sharing a sentence is not in itself a finding about the gene and the disease.
ischemia (continued). "Moreover, as per our findings, ischemia led to an increase in the HDAC9 expression in the brain of wild type mice, while the loss of HDAC9 was observed to suppress the release of IL-1β, IL-6, IL-18, and TNF-α in the mouse cortex, hippocampus, and hypothalamus after I/R injury." (PMID 33584204, 2020). "Anti-IL-6 neutralizing antibodies were also found to mitigate increases in BBB permeability due to ischemia in vivo, suggesting that IL-6 may be partially responsible for BBB dysfunction following disorders such as ischaemic injury as observed in the ovine fetus." (PMID 33120941, 2020). "Fifth, the final models were adjusted for several important predictors of cardiometabolic risk including age, sex, renal function, a summed stress score (i.e., a marker of myocardial scar and ischemia), and markers of systemic inflammation (i.e., IL-6 and hs-CRP), there may be residual confounding." (PMID 30886968, 2018). "Furthermore, endogenous zinc release was induced by cerebral ischaemia–reperfusion, resulting in increased expression of IL-1β, IL-6, TNFα, and the microglial M1 surface marker CD16/32, without hippocampal neuronal cell loss, in addition to impairments in object recognition memory." (PMID 28240322, 2017). "During ischemia, inflammatory cells like macrophages may migrate into the ischemic myocardium and produce proinflammatory cytokines and chemokines, including TNFα, interleukin 6 (IL6), IL-1β, and monocyte chemotactic protein 1 (MCP-1), which further exacerbate myocardial I/R injury." (PMID 27190998, 2016). "Therefore, the increase of the flare value in CRVO may be related to increased production of inflammatory factors (such as VEGF, sICAM-1, and IL-6) due to inflammation and/or ischemia." (PMID 24325604, 2013). "ATN from ischemia and nephrotoxins are the most common causes of AKI in hospitalized patients and distinguishing pre-renal azotemia from ATN remains a challenging clinical dilemma, thus, increased urine IL-6 may have clinical utility for this purpose." (PMID 20942931, 2010). "In mice, increased IL-6 mRNA and other inflammatory mediators in cardiac ischemia and reperfusion were reduced by cardiac myocyte–specific PIEZO1 deletion, suggesting a role for cardiac myocyte PIEZO1 in regulating IL-6." (PMID 40721314, 2025). "For instance, in a rat model of intestinal ischemia–reperfusion-induced ALI, suppression of IL6 significantly improved lung pathology." (PMID 41441024, 2025). "In vitro, brain microvascular endothelial cells upregulated ICAM-1, IL-6, and VEGFR-2 expression when exposed to recombinant α-Syn at the beginning of ischemia and to a larger extent when α-Syn was preconditioned for 18 hours in hypoxia." (PMID 40964705, 2025). "Patients with CRVO and ischemia have significantly higher vitreous fluid levels of IL-6 and VEGF, and these are significantly correlated with the extent and severity of ischemia and ME." (PMID 39272767, 2024). "In a mouse model in which ischemia was pharmacologically induced, it was observed that TREM-1 promotes the production of IL-1β, IL-18, IL-6, CXCL-2, MCP-1, and CXCL-1 in microglia." (PMID 39062850, 2024). "TLR4−/− mice and mice given LPS-RS, a TLR4 antagonist, exhibited decreased systemic IL6 and TNF-α levels after hindlimb ischemia, implicating the role of TLR4 in ischemia-induced systemic inflammatory cytokine production." (PMID 38510939, 2024). "Cytokines, namely, IL‐1β, TNF‐α, IL‐6 and IFN‐γ, rise 24 h post ischemia in a tMCAO model, and reducing the concentrations of these cytokines are highly advantageous to IS treatment." (PMID 37132060, 2023). "Inflammatory signaling is activated and completed by blood-derived leukocytes, which penetrate the brain during ischemia and produce inflammatory cytokines and proinflammatory mediators, including TNF-α, IL-6, and ICAM-1." (PMID 37361203, 2023).
ischemia (continued). "Our findings on cytokine kinetics are consistent with previous studies showing an increase of TNF-α, IL-6, and IL-8 within minutes after the start of surgery, changes being correlated with CPB and ischemia duration." (PMID 37522081, 2023). "The neuroprotective mechanisms of 6 mg/kg purpurin were evaluated in terms of anti-inflammatory responses in the hippocampus using an ELISA assay for IL-1β, IL-6, and TNF-α 6 h after ischemia." (PMID 35094304, 2022). "Ischaemia led to a significant increase in MPO activity and TNF-α, and IL-6 concentrations in the ovaries when compared with the sham-operated animals." (PMID 36200598, 2022). "IL-1β, IL-6, and TNF-α levels were significantly decreased 4 days in the hippocampus after ischemia compared to 6 h post-ischemic group, respectively." (PMID 35094304, 2022). "In primary rat cerebellar neuronal-glial cell cultures affected by ischemia, propolis significantly protected the cultures from hypoxia-induced elevation of TNF-α, IL-1β and IL-6." (PMID 36500579, 2022). "The expression of serum IL-6 and TNF-α in the mild hypothermia therapy group was significantly lower than that in the ischemia reperfusion group." (PMID 34422094, 2021). "mRNA levels of proinflammatory cytokines, IL-1α, IL-6, and TNF-α, were significantly higher in the I/R group 2 h after the reperfusion period following ischemia compared with the control group (IL-1α, p < 0.05; IL-6, p < 0.0001; TNF-α, p < 0.01)." (PMID 33843175, 2021). "In the present study, transient ischemia significantly increased lipid peroxidation and pro-inflammatory cytokines IL-1β, IL-6, and TNF-α in the hippocampus 6 h after ischemia." (PMID 34203930, 2021). "We measured the expression of proinflammatory cytokines (IL-1β, IL-6, and TNF-α) in the ischemia penumbra 24 h after reperfusion." (PMID 32917229, 2020). "The inflammatory cytokines rising in COPD, such as IL-6, C-reactive protein and TNF-α, would also lead to ischemia, which further implies that inflammation can trigger pulmonary hypertension by changing the blood vessels of the pulmonary cycle." (PMID 33108241, 2020). "We found that CSO treatment significantly inhibited the hyperactivation of microglia and astrocytes and significantly decreased the expression levels of proinflammatory cytokines (IL-1β, IL-6, and TNF-α) in the ischemia penumbra after MCAO-R injury." (PMID 32917229, 2020). "In the present study, we observed transient increases in pro-inflammatory cytokines, such as IL-1β, IL-6, and TNF-α in the spinal cord after ischemia, indicating inflammation." (PMID 33050051, 2020). "The pre-intracere-broventricular injection of IL-6 inhibited the activation of JNK and ERK 24h after global ischemia, which proposed that the neuroprotection of IL-6 was exerted in the late phase after 24h." (PMID 33269103, 2020). "Proinflammatory agents, such as interleukin (IL)-6, IL-1, and TNF-α, promote the developing of the harmful phlogosis that takes place in the brain after the ischemia." (PMID 32899616, 2020). "Especially IL- 1β, IL-6 and TNF-α play a primary role in hippocampus inflammation responding to transient global ischemia/reperfusion." (PMID 32150581, 2020). "Consistently, we found that ischemia-induced TREM-1 promoted IL-1β, IL-18, IL-6, CXCL-2, MCP-1, and CXCL-1 productions in microglia as well as the expression of MPO and ICAM-1 following ischemic injury." (PMID 31324751, 2019). "We detected the expression of mRNAs for various inflammatory cytokines (IL-1β, TNF-α, IL-6, IL-10, and TGF-β) in the cortex ipsilateral to sites of ischemia 24, 48, and 72 h after reperfusion." (PMID 27549161, 2016). "In the ischemia + PPG group, the TNF-α, IL-1β and IL-6 levels in the serum were significantly increased, the expression of ICAM-1 mRNA was increased, although without a significant difference, and the expression of NF-κB was increased." (PMID 25667680, 2015).
ischemia (continued). "In the ischemia + PPG group, the serum levels of TNF-α, IL-1β and IL-6 were significantly increased compared with those in the ischemia group (P<0.05 or P<0.01)." (PMID 25667680, 2015). "Under normal physiological conditions, levels of IL-6 remain low, however, IL-6 is elevated rapidly in the PNS after axotomy and in the CNS after brain damage including ischemia and trauma." (PMID 25992975, 2015). "Compared to normal mice, diabetic mice showed reduced MCP-1, IL-6, and CCR2 gene expression in the brain at 6 h post-ischemia." (PMID 24886035, 2014). "During ischemia, cytokines, such as TNF-α, IL-1β, IL-6, and chemokines such as cytokine-induced neutrophil chemoattractant (CINC) and MCP-1 are produced by a variety of activated cell types, including endothelial cells, microglia, astrocytes and neurons." (PMID 23663236, 2013). "During ischemia, cytokines, such as TNF-α, IL-1β, IL-6, and chemokines such as CINC and MCP-1 are produced by a variety of activated cell types, including endothelial cells, microglia, astrocytes and neurons." (PMID 22196138, 2011). "In the two ischemia groups our measurements indicated an mRNA up-regulation of TNF-α, IL-1β, and IL-6 that was unaffected by COX-2 enzyme blockage." (PMID 17150094, 2006). "Additionally, the E-MSC-treated ischemia groups showed a substantial reduction in inflammatory cytokine (TNF-α, IL-1β, IL-6, and TGF-β) levels and a notable increase in angiogenetic cytokine (ANG1, FGF, VEGF, and PDGF) levels compared to the control group." (PMID 40595285, 2025). "After ischemia onset, microglia are rapidly activated to the M1 type along with GSK-3β overactivation and thus secrete a variety of proinflammatory factors, such as TNF-α, IL-1, and IL-6, leading to an inflammatory cascade." (PMID 41292262, 2025). "Mechanical compressive ischemia was alleviated under the heat induced by warm needle acupuncture, which can also increase 6-keto-PGF1α, reduce hs-CRP, IL-6, and TNF-α levels, increase the content of endothelial growth factors, promote local revascularization, and reduce inflammation." (PMID 40860976, 2025). "Studies have shown that low levels of TNF-α may have a protective effect on the heart by enhancing myocardial tolerance to ischemia, and TNF-α may inhibit the expression of inflammatory cytokines such as IL-1, IL-2, and IL-6 in the heart." (PMID 40284832, 2025). "Comparing GCA patients with disease‐related ischemia episodes to those without ischemic sequelae, the findings showed lower circulating levels of IL‐6, lower IL‐6 immunohistochemistry expression scores, and lower IL‐6 mRNA levels." (PMID 39817601, 2025). "In summary, GCA patients with ischemic outcomes exhibited lower tissue expression and circulating levels of IL‐6 in comparison to those without ischemia episodes." (PMID 39817601, 2025). "Interestingly, ischemia-induced increases in GFAP signal intensity were blocked by FA, whereas FA-induced increased IL-6 intensity in these ganglia." (PMID 38147796, 2024). "Blood samples collected pre‐ischemia and 24 h post‐reperfusion, along with muscle tissue samples after 24 h, demonstrated that EGb761 at 1000 μg/mL effectively inhibited IL‐6 and TNF‐α secretion in RAW 264.7 cells without cytotoxicity." (PMID 38839736, 2024). "Together, these experiments show that the initial IL-6 formation immediately after release of ischemia was not under the control of the A2bR, despite the highly elevated extracellular adenosine levels." (PMID 36943408, 2023). "While adenosine via the A2bR was an important regulator of cardiac IL-6 formation in the remodeling phase, it did not appear to influence IL-6 immediately after release of acute ischemia." (PMID 36943408, 2023). "In the literature, many studies focus on different predictive systemic and peritoneal drain biomarkers (inflammatory, microbiological, markers of ischemia) and frequently mention CRP, procalcitonin (PCT), neutrophil-to-lymphocyte ratio, white blood cell count and IL-6." (PMID 38098074, 2023).
ischemia (continued). "Pro-inflammatory cytokines, such as IL-1β, IL-6, and TNF-α, were significantly increased in the hippocampus after ischemia induction, and Tat-CHIP attenuated the increase in pro-inflammatory cytokine release, suggesting the anti-inflammatory potential of Tat-CHIP in ischemic damage." (PMID 36450819, 2022). "Studies have implied that inflammatory factors such as IL-6, TNF-α are targets of miRNA-149-5p, and the miRNA improves BBB function and integrity by reducing the mentioned factors following cerebral ischemia and decreases ischemia-reperfusion injury." (PMID 35871268, 2022). "In the purpurin-treated ischemic group, IL-1β, IL-6, and TNF-α levels were significantly lower than those in vehicle-treated ischemic group and were 203.2%, 178.2%, and 626.1% of those in the control group 6 h after ischemia, respectively." (PMID 35094304, 2022). "We observed the levels of IL-6, IL-1β, and TNF-α in the hippocampus 6 h after ischemia because these pro-inflammatory cytokines are increased biphasically, with a prominent increase at this early period after ischemia." (PMID 33435613, 2021). "There was a significant increase in the median level of interleukin 6 in the group without ischemia and a significant decrease in VEGF in both groups." (PMID 34907265, 2021). "When ischemia occurs, the expression of mmu-miR-155 was significantly upregulated, and inhibiting mmu-miR-155 could reduce the secretion of TNF-α, IL6, IL1β, and IFN-γ induced by neuroinflammation." (PMID 34457020, 2021). "Moreover, magnesium isoglycyrrhizinate suppressed the levels of TNF-α, IL-1β, IL-6, antioxidant enzymes (SOD, GSHPx), iNOS, and caspase-3 in ischemia-reperfusion injury model rats." (PMID 34220502, 2021). "Moreover, the pro-inflammatory factors COX-2, IL-6, IL-1β, and TNF-α were rarely expressed in the sham group, while their expression was remarkably elevated after ischemia." (PMID 35082676, 2021). "In addition, we observed the significant reduction of pro-inflammatory cytokines such as IL-6, IL-1β, and TNF-α in hippocampal homogenates 6 h after ischemia." (PMID 33435613, 2021). "Moreover, treatment with 100 mg/Kg bacailin significantly reduces the levels of pro-inflammatory cytokines, including IL-1β, IL-6, and TNF-α in the hippocampus of ischemia mice." (PMID 32084011, 2020). "It was also found that the PAC1 was upregulated along with IL-6 at only 3 to 7 days in hippocampal astrocytes rather than microglia after ischemia." (PMID 33269103, 2020). "Patients with CRVO with ischemia had significantly higher vitreous fluid levels of IL-6 than patients with CRVO without ischemia, and IL-6 levels correlated significantly with the extent of macular edema." (PMID 33121094, 2020). "The splenic inflammatory response induced by cerebral ischemia was inhibited by αCD147 treatment as demonstrated by the reduced expression of cytokines (TNFα, IL-6, IL-1β) and monocyte chemoattractant protein-1 (MCP-1) in the spleen at 4 and 24 h after ischemia onset." (PMID 31666088, 2019). "In the first 3–12 h after myocardial ischemia, expression of IL-1β and IL-6 was significantly increased in both ischemia and non-ischemic myocardium." (PMID 31287006, 2019). "Those with the M1 polarized phenotype secrete pro-inflammatory cytokines, such as IL-6, IL-1β, and TNF-α, which may further aggravate neuroinflammation in the peri-infarct region after ischemia and reperfusion injury." (PMID 31640144, 2019). "There was a notable reduction in frequency of CD8+ IFNγ+ T cells in both groups following anti-IL-6, but the effect size was markedly greater in ischemic grafts (49.04 ± 0.52 vs. 106.74 ± 2.97 fold reduction in CD8+ IFNγ+ infiltration, control vs. ischemia, ***p < 0.001, respectively, n = 3/group)." (PMID 29410442, 2018). "Patients with mitochondrial dysfunction had statistically significant higher IL-6 and IL-8 compared to those with no ischemia/no mitochondrial dysfunction; they also had higher IL-6 than patients with ischemia." (PMID 30301230, 2018).
ischemia (continued). "We found that in this unique population of women with symptomatic ischemia, non-obstructive CAD and preserved EF at baseline, serum IL-6 was associated with an increased risk of HF hospitalization in a continuous fashion without evidence of a threshold." (PMID 28542263, 2017). "In women with signs and symptoms of ischemia, non-obstructive CAD and preserved EF, the inflammatory biomarker IL-6 was predictive of HF-hospitalization and all-cause mortality, while SAA predicted all-cause mortality." (PMID 28542263, 2017). "In women with signs and symptoms of ischemia, non-obstructive CAD and preserved EF, elevated IL-6 predicted HF hospitalization and all-cause mortality, while SAA level was only associated with all-cause mortality." (PMID 28542263, 2017). "Indeed, EP4 agonist significantly attenuated the production of TNFα, IL-6, IL-1β, and MCP-1 as well as macrophage infiltration in the heart after ischemia." (PMID 27190998, 2016). "There is a fine balance in the effects of IL-6/STAT3 signaling, since STAT3 activity in acute ischemia is cardioprotective, while continuous activation could be detrimental." (PMID 25997003, 2015). "In cultured microglia, activation by several stimuli depends on NHE1 mediated H+ homeostasis and inhibition of NHE1 with HOE 642 also reduced the production of superoxide anions as well as proinflammatory cytokines IL-1β, IL-6, and TNF-α induced by LPS or in vitro ischemia." (PMID 24392123, 2014). "Vitreous fluid levels of both VEGF and IL-6 were significantly higher in patients with BRVO/CRVO patients with ischemia than in those without ischemia." (PMID 25152567, 2014). "Mild positivity of immunoreaction (tryptase, CD15, IL-1β, IL-6, IL-8, TNF-α) and stronger reactivity for IL-15, MCP-1 in areas where depletion of cellular antigens (myoglobin and cardiac troponin) is detectable within 30 – 40 minutes from ischemia." (PMID 24989171, 2014). "In summary, we demonstrate that neuroprotection with D-JNKI1 does not significantly reduce brain and early systemic secretion of IL-6 and KC after moderate ischemia and that the spleen is not the major source of the early systemic secretion." (PMID 22533966, 2012). "Within the first hours after onset of ischemia affected brain cells produce and secrete proinflammatory cytokines including monocyte chemoattractant protein-1 (MCP-1), interleukin-6 (IL-6), interleukin-1β (IL-1β), tumor necrosis factor-α (TNF-α) and granulocyte-colony stimulating factor (G-CSF)." (PMID 22031820, 2011). "Collectively, these findings indicate that, within the studied range, neither the choice of cardioplegic solution nor the duration of ischemia had a statistically significant impact on the myocardial release of IL-4, IL-6, IL-10, leptin, TNF-α following ischemia/reperfusion injury." (PMID 40729334, 2025). "In the initial stages of ischemia, neural and glial cells in the brain are activated by the lack of blood flow and oxygen, leading to the release of inflammatory mediators such as tumor necrosis factor-alpha (TNF-α), interleukin-1 beta (IL-1β), and interleukin-6 (IL-6)." (PMID 40421420, 2025). "In addition, smoking induces coronary vasoconstriction, stimulates the renin-angiotensin system, and increases inflammatory cytokines (e.g., interleukin-6 (IL-6), tumor necrosis factor-alpha (TNF-α)), contributing to plaque development, instability, and ischemia." (PMID 41306139, 2025). "Based on this information, we studied pro-inflammatory (IL-6, TNF-alpha, and IL-1beta) and anti-inflammatory (IL-10 and TGF-beta) cytokines with ELISA to clarify whether there were any corresponding changes between them during different stages of ischemia." (PMID 37822799, 2023). "In addition, Tat-PGAM1, but not Control-PGAM1, significantly decreased microglial activation and secretion of pro-inflammatory cytokines, such as interleukin (IL)-1β, IL-6, and tumor necrosis factor (TNF)-α induced by ischemia in the ventral horn of the spinal cord." (PMID 33050051, 2020).